NOS3 (nitric oxide synthase 3)
Diseases named in the same sentence as NOS3 in open-access papers (continued):
Sharing a sentence is not in itself a finding about the gene and the disease.
endotoxemia (4 papers, 2014 to 2024). "Since citrulline supplementation is suggested to be a more preferential substrate for NOS3, to result in an enhanced arginine availability, we supplemented citrulline in control and tissue specific arginase-I-deficient mice during prolonged endotoxemia." (PMID 25699985, 2015). "Therefore, targeting endothelial arginase can be a promising therapeutic option to prevent vascular dysfunction caused by an impaired NOS3-mediated NO production, as present during endotoxemia." (PMID 24465919, 2014). "Furthermore, downregulation of Nos3 expression during endotoxemia may further contribute to the impaired NO production during endotoxemia in these Nos2-deficient animals." (PMID 34769369, 2021). "L-citrulline supplementation during endotoxemia resulted in enhanced plasma citrulline concentrations in control, Nos2−/− and Nos3−/− mice." (PMID 34769369, 2021). "We therefore investigated the effect of L-citrulline supplementation in Nos2−/−, Nos3−/−, and Nos2−/−/Nos3−/− mice on intracellular arginine availability, jejunal NO production and microcirculatory flow in a prolonged endotoxemia model." (PMID 34769369, 2021). "This increased NOS2 activity is suggested to contribute to the decreased NOS3 derived NO production and the depressed microcirculatory flow during endotoxemia." (PMID 25699985, 2015). "Competition for the amino acid arginine by endothelial nitric-oxide synthase (NOS3) and (pro-)inflammatory NO-synthase (NOS2) during endotoxemia appears essential in the derangement of the microcirculatory flow." (PMID 34769369, 2021). "The increased NO production due to endotoxemia in Nos3−/− mice was not further increased by L-citrulline supplementation (p = 0.9)." (PMID 34769369, 2021). "This study investigated the role of NOS2 and NOS3 combined with/without citrulline supplementation on the NO-production and microcirculation during endotoxemia." (PMID 34769369, 2021). "Furthermore, we showed that, in the absence of arginase-1 in endothelial cells or macrophages, only NOS2-derived NO production significantly increased during endotoxemia, whereas NOS3-derived NO production did not benefit from the arginase-1 deficiency." (PMID 34769369, 2021). "Endotoxemia reduced the total number of perfused vessels and the number of perfused vessels per villus in control and Nos2−/− mice, but did not alter these parameters in Nos3−/− or Nos2−/−/Nos3−/− mice." (PMID 34769369, 2021). "Our findings further reveal that, in the absence of Nos3, endotoxemia and supplementation of L-citrulline does not affect the microcirculation, demonstrating that the positive effects of L-citrulline supplementation depend on the presence of a functional NOS3 enzyme." (PMID 34769369, 2021). "This study confirms that L-citrulline supplementation enhances de novo arginine synthesis and NO production in mice during endotoxemia with a functional NOS3-enzyme (control and Nos2−/− mice), as this beneficial effect was absent in Nos3−/− or Nos2−/−/Nos3−/− mice." (PMID 34769369, 2021).
glioma (4 papers, 2012 to 2022). A benign or malignant brain and spinal cord tumor that arises from glial cells (astrocytes, oligodendrocytes, ependymal cells). "Nos2 was clearly overexpressed in the xenografted glioma cells when compared to Nos1 and Nos3." (PMID 25768009, 2015).
Hepatic steatosis (4 papers, 2021 to 2025). Steatosis is a term used to denote lipid accumulation within hepatocytes. "PSO ameliorated lipid profiles, body weight, reduced hepatic steatosis/pathological damage through the in vivo experiment, and is probably associated with the potential mechanism activating the PI3K/Akt/NOS3 signaling pathway." (PMID 41376062, 2025).
Infertility (4 papers, 2012 to 2025). "In this study, we also demonstrated a significant positive association of NOS3 rs1799983 variants with higher levels of sperm DNA fragmentation (β = 0.223, P = 0.044) in infertile men." (PMID 25517965, 2014). "Nitric oxide synthase 3 (NOS3) as the target gene of bta-miR-2889 was enriched in calcium signaling pathway and oxytocin signaling pathway, which mutants might cause oxidative sperm DNA damage and increased risk of infertility in men." (PMID 32481702, 2020).
liver fibrosis (4 papers, 2022 to 2024). "Enrichment analyses of these core genes showed that cellular response to external stimulus, oxidative stress, inflammation response, ECM remodeling, NOS3 activation and regulation and VEGF signaling pathway were the predominant biological processes and pathways in CHSGS treating liver fibrosis." (PMID 35791909, 2022).
lung carcinoma (4 papers, 1998 to 2023). "The NOS3 activity in LUAD samples was higher compared to other types of lung cancers and normal lung samples." (PMID 38107574, 2023). "The Ca2+-dependent NOS activity, which indicates NOS1 and NOS3 expression, was significantly reduced in lung carcinomas compared with adjacent non-tumour tissue (P < 0.004)." (PMID 9683299, 1998).
mental disorder (4 papers, 2018 to 2020). A disease that has its basis in the disruption of mental process. "In our review, we have summarized information regarding all NOS1, NOS2, NOS3, and NOS1AP single nucleotide variants (SNVs) involved in the development of mental disorders and neurological diseases/conditions." (PMID 32111088, 2020). "Furthermore, three active ingredients, ATR3, ATR15, and ATR102, were shown to interact with MAOA, MAOB, and NOS3, which are related to inflammation and play a role in the pathogenesis and symptoms of mental disorders." (PMID 32802132, 2020). "In our review, we have decided to summarize information regarding all NOS1, NOS2, NOS3, and NOS1AP SNVs involved in the development of mental disorders and neurological diseases/conditions." (PMID 32111088, 2020).
Miscarriage (4 papers, 2022 to 2025). A pregnancy that ends at a stage in which the fetus is incapable of surviving on its own, defined as the spontaneous loss of a fetus before the 22th week of pregnancy. "Another study conducted in Russia in 2019 showed a positive association between rs2070744 of the NOS3 gene with miscarriage." (PMID 36313260, 2022).
pancreatic cancer (4 papers, 2016 to 2021). "In pancreatic cancer, NOS3 promoted tumor maintenance through the PI3K-Akt-NOS3-RAS (wild type) pathway." (PMID 33747912, 2021). "Corroborating the role of eNOS in RAS-driven cancers, genetic ablation of NOS3 gene disrupted pancreatic carcinoma and papilloma development and improved mice median survival." (PMID 34502464, 2021). "Knockdown of NOS3 showed that active NOS3 is necessary both for initiation and maintenance of human pancreatic cancer cells." (PMID 26841718, 2016). "An increase in NOS2 and NOS3 expression is found in PDAC, and genetic deficiency of endothelial NOS (NOS3) decreased the number of precursor lesions in mouse model of pancreatic cancer but failed to significantly enhance the survival of mice with PDAC." (PMID 27367029, 2016). "However, genetic ablation of NOS3 or endothelial NOS inhibited the development of precursor lesions or pancreatic intraepithelial neoplasia (PanINs) in a genetically engineered mouse model of pancreatic cancer." (PMID 27367029, 2016).
pneumonia (4 papers, 2014 to 2022). An acute, acute and chronic, or chronic inflammation focally or diffusely affecting the lung parenchyma, caused by an infection in one or both of the lungs (by bacteria, viruses, fungi, or mycoplasma.). "Statins can increase levels of NOS3 and have been associated with beneficial effects on incidence of hospitalization for pneumonia and subsequent mortality." (PMID 25317947, 2014). "NOS-3 levels are increased by estrogens and statins, and authors found that receiving estrogenic therapy, statin therapy, or both was associated with a reduced incidence of pneumonia requiring hospitalization in women." (PMID 35852675, 2022). "Epidemiologic data show decreased hospitalization for pneumonia in women receiving estrogen or statins (known to activate NOS3)." (PMID 25317947, 2014). "Genetic deletion of NOS3 greatly reduced survival in female mice with pneumonia, and transgenic overexpression of NOS3 increased bacterial clearance in male mice, supporting the functional importance of this pathway." (PMID 25317947, 2014). "We conclude that estrogen mediates greater host resistance to pneumonia in female mice via effects on the constitutively expressed NOS3 in lung macrophages." (PMID 25317947, 2014). "Pharmacologic agents that enhance NOS3 function improved resistance in mouse models of both primary lung infection and post-influenza secondary pneumonia, suggesting a strategy to enhance resistance to common and serious lung infections." (PMID 25317947, 2014). "Pharmacologic targeting of NOS3 with statins or another small-molecule compound (AVE3085) enhanced macrophage bacterial killing, improved bacterial clearance, and increased host survival in both primary and secondary (post-influenza) pneumonia." (PMID 25317947, 2014).
psoriasis (4 papers, 2017 to 2021). An autoimmune condition characterized by red, well-delineated plaques with silvery scales that are usually on the extensor surfaces and scalp. "Recent studies have also found interleukin 1β (IL-1β), tumor necrosis factor (TNF), vitamin D receptor (VDR), nitric oxide synthase 3 (NOS3), and other genes to be overexpressed in psoriasis patients (GOF)." (PMID 29292715, 2017). "Among all the targets, the top three were PTGS2, MAPK14, and NOS3 in terms of Degree, and all of them have been demonstrated to play important roles in the pathogenesis of psoriasis, such as inflammatory infiltration, abnormal differentiation of keratinocytes, and oxidative stress injury." (PMID 32655662, 2020). "Instead, the NOS3 variants −786 T/C and intron 4 VNTR corresponded with higher susceptibility to psoriasis but not with HT and CVD." (PMID 34445769, 2021).
abdominal aortic aneurysm (3 papers, 2018 to 2022). Enlargement and ballooning of the vessel that supplies arterial blood to the abdomen, pelvis and legs. "Reports examining HPH-1 mice, a mouse model with uncoupled NOS3, showed rapidly developing abdominal aortic aneurysms as well as aortic rupture upon infusion of angiotensin II." (PMID 32801116, 2020). "Reports by Kuhlencordt and colleagues show that double-knockout Apoe/Nos3 models develop severe cardiovascular complications, including spontaneous abdominal aortic aneurysms and dissection." (PMID 32801116, 2020).
Achalasia (3 papers, 2023 to 2024). A disorder of esophageal motility characterized by the inability of the lower esophageal sphincter to relax during swallowing and by inadequate or lacking peristalsis in the lower half of the body of the esophagus. "On the other hand, in the digestive tract, the production of NO by the neuronal NOS (nNOS, encoded by NOS1 gene) explains that the patients mutated in NOS3 do not suffer from achalasia." (PMID 36941667, 2023).
anaphylaxis (3 papers, 2017 to 2024). An acute hypersensitivity reaction that occurs from exposure to an allergen. "NOS3 upregulation and consequent NO production is protective under normal conditions, though may be deleterious in a model of experimental anaphylaxis." (PMID 29104573, 2017).
aortic valve disease (3 papers, 2019 to 2023). "Observations that Krox20 regulates nitric oxide activity through activation of Nos3 proximal promoter in vivo and in vitro suggest that interaction between different pathways may be implicated in aortic valve disease such as BAV." (PMID 31684048, 2019). "Here, we report BAV phenotype in compound heterozygous Krox20;Nos3 mice, and show a direct activation of Nos3 expression by Krox20, demonstrating a genetic link between these two genes already known to be implicated in aortic valve disease including BAV." (PMID 31684048, 2019). "In addition, Nos3−/−; Notch1+/− mice develop aortic valve disease, indicating a genetic interaction between Nos3 and Notch1 in calcific progression." (PMID 34239905, 2021). "Interestingly, expression of Notch1, which is regulated by Nos3 signaling in aortic valve disease, is also reduced in Krox20−/− embryos." (PMID 31684048, 2019).
Arthritis (3 papers, 2005 to 2016). Inflammation of a joint. "The upregulated expression of TNF-α, IL-1α, IL-1β, IL-4R, P-selectin, MIP-1α (CCL3), MCP-1 (CCL2), NOS2 and NOS3 demonstrated in the present study is in agreement with previous observations of the dependency of the rat SCW-induced arthritis model on these mediators." (PMID 15642130, 2005).
colitis (3 papers, 2014 to 2024). Inflammation of the colon. "Although the role of nitric oxide in IBD is unclear, a role for NOS3 in the development of colitis has been demonstrated using murine models." (PMID 35805947, 2022).
diabetic neuropathies (3 papers, 2015 to 2024). "Many contradictory results have been reported on the role of NOS3 variants in relation to diabetic neuropathies as they seem to be significantly influenced by population-specific effects." (PMID 26074879, 2015). "Particularly the NOS3 VNTR 4a/b variant is suspected of having a haplotype-dependent effect on diabetic microvascular complications and diabetic neuropathy." (PMID 26074879, 2015). "This review suggests that polymorphism within ACE, AKR1B1, APOE, MTHFR, NOS3, and VEGF may act as common genetic risk factors for the diabetic neuropathies in T2DM." (PMID 26074879, 2015).
Headache (3 papers, 2021 to 2022). Cephalgia, or pain sensed in various parts of the head, not confined to the area of distribution of any nerve. "Over the past 15 years, works aimed at finding associations of NOS1, NOS2, and NOS3 genes with the development and course of headaches (H) have been carried out using the example of patients with M." (PMID 34200123, 2021). "In parallel with Turkish studies, a noteworthy study of genes NOS1 and NOS3 SNVs as risk factors for the development of medication overuse headaches (in patients with M) was carried out in the Japanese population." (PMID 34200123, 2021). "Quite a few studies have considered associations of NOS3 gene SNVs with headache." (PMID 33809023, 2021).
hyperphosphatemia (3 papers, 2017 to 2021). Abnormally high level of phosphate in the blood. "In summary, aging-related hyperphosphatemia seems to be associated with age-related changes in vascular relaxation by NOS3 reduction via ROS-induced NFκB activation." (PMID 34439556, 2021). "The presence of the antioxidant NAC, a precursor of glutathione, avoided the reduction in NOS3 expression, suggesting that ROSs are mediating hyperphosphatemia-induced NOS3 downregulation." (PMID 34439556, 2021). "In order to explore a possible mechanism involved in the reduction in NOS3 expression induced by hyperphosphatemia, in vitro studies were performed in human endothelial cells, analyzing the role of oxidative stress in this effect." (PMID 34439556, 2021). "We propose here that hyperphosphatemia induces an imbalance oxidant/antioxidant in favour of oxidative stress, which on one hand reduces endothelium-dependent relaxation through NOS3 reduction and on the other hand increases inflammation and the fibrosis increasing vascular stiffness." (PMID 34439556, 2021).
leukemia (3 papers, 2017 to 2024). A malignant (clonal) hematologic disorder, involving hematopoietic stem cells and characterized by the presence of primitive or atypical myeloid or lymphoid cells in the bone marrow and the blood. "Interestingly, MLL-AF9 leukemia occurrence was significantly delayed in Nos3-KO mice (top), Nos3-KO mice were active and healthy at the time wild-type (WT) mice showed clear signs of disease and were euthanized." (PMID 28870739, 2017). "To test whether the exogenous production of NO has a role in leukemia transplantation and progression, we transplanted leukemic cells from two models of murine AML (MLL-AF9 and MLL-ENL) in Nos3-knockout (Nos3-KO) recipient mice and studied the status of the vasculature and disease progression." (PMID 28870739, 2017).
multiple sclerosis (3 papers, 2017 to 2021). A progressive autoimmune disorder affecting the central nervous system resulting in demyelination. "The association study of NO-encoding genes with multiple sclerosis (MS) demonstrated no statistically significant results in relation to the NOS1 gene, unlike other enzymes of this family (see Section 2.3.7 and Section 2.4.10 on “Multiple Sclerosis” regardingNOS2 and NOS3)." (PMID 32111088, 2020).
osteomyelitis (3 papers, 2019 to 2022). An acute or chronic inflammation of the bone and its structures due to infection with pyogenic bacteria. "We have previously found that variants in the genes of IL-1α, MMP1, TLR4 receptor, endothelial nitric oxide synthase (NOS3), Bax and tPA also contribute to the risk of developing osteomyelitis with prevalences of between 3.8% and 65.3%." (PMID 31647805, 2019).
ovarian carcinoma (3 papers, 2015 to 2021). A malignant neoplasm originating from the surface ovarian epithelium. "Promotion of EMT by either HOXB13 or ALX4 expression was also observed in another ovarian cancer cell line, NOS3." (PMID 25944620, 2015). "NOS1 and NOS3 mRNA levels were detected in A2780 and 2008 cells, but were almost undetectable in ES2 cells and other ovarian cancer cell lines that we tested." (PMID 25924901, 2015).
Priapism (3 papers, 2013 to 2022). A painful and harmful medical condition in which the erect penis doesn't return to its flaccid state, despite the absence of both physical and psychological stimulation, within four hours. "However, our results showed statistically significant differences between NOm levels in the ancestral and minor alleles of NOS3–786 in the SCA priapism- group (p = 0.0118); no similar association was observed among priapism+ patients." (PMID 33539452, 2021).
pulmonary fibrosis (3 papers, 2020 to 2023). Chronic progressive interstitial lung disorder characterized by the replacement of the lung tissue by connective tissue, leading to progressive dyspnea, respiratory failure, or right heart failure. "Following lung injury, endothelial cells increase the expression of nitric oxide synthase 3 (NOS3) to synthesize endothelial nitric oxide synthase, which causes nitric oxide activate soluble guanylate cyclase, thereby promoting inactivation of lung fibroblasts and regression of pulmonary fibrosis." (PMID 35563849, 2022). "Investigations aimed at understanding whether restoring Nos3 expression in aged animals may have beneficial effects in reestablishing endothelial homeostasis and limiting lung fibrosis may be an interesting future subject of study." (PMID 32691484, 2020).
rheumatoid arthritis (3 papers, 2015 to 2024). A chronic, systemic autoimmune disorder characterized by inflammation in the synovial membranes and articular surfaces. "The inflammatory targets that mediate rheumatoid arthritis mainly include (TNF, PTPN11, IL6, etc.); the main targets that mediate RA oxidative stress are NOS3; the targets that mediate the destruction of extracellular matrix tissue in RA mainly include (MMP9, MMP2, ANXA5, etc.)." (PMID 38238321, 2024). "According to the results of molecular docking, in the context of rheumatoid arthritis, phytocannabinoids may bind to important target proteins such as PIK3CA, AKT1, MAPK9, PRKCD, BRAF, IGF1R, and NOS3." (PMID 36983855, 2023).
systemic lupus erythematosus (3 papers, 2009 to 2024). An autoimmune multi-organ disease typically associated with vasculopathy and autoantibody production. "No significant variations in p-NOS3 were documented in our study, despite a trend toward a higher p-NOS3/NOS3 ratio observed upon treatment with the plasma of lupus mice." (PMID 39061948, 2024).
aortic atherosclerosis (2 papers, 2018 to 2022). A atherosclerosis that involves the aorta. "We previously found that NOS3 prevents aortic atherosclerosis in mice, at least by regulating the expression of MMP-13, by yet unknown mechanisms." (PMID 30347750, 2018).